TGIF1 (TGFB induced factor homeobox 1)
Diseases named in the same sentence as TGIF1 in open-access papers (continued):
Sharing a sentence is not in itself a finding about the gene and the disease.
breast carcinoma (continued). "To determine whether the reduced presence of single cells and breast cancer micro-metastases 5 days after tumor cell injection results in a decreased metastatic burden, we analyzed the establishment of bone metastases in Tgif1−/− and Tgif1+/+ mice." (PMID 32272947, 2020). "In support of this finding, knockdown of Tgif1 in MDA-MB-231 breast cancer cells reduced the presence of lung metastases in mice, suggesting that Tgif1 promotes cell-autonomous breast cancer growth and metastasis." (PMID 32272947, 2020). "Absence of Tgif1 in osteoblasts resulted in suppressed breast cancer cell migration and bone metastases, which is mediated through increased Semaphorin 3E (Sema3E) expression." (PMID 35994202, 2022). "In this study, we demonstrate that lack of Tgif1 also restricts the progression of breast cancer bone metastases." (PMID 32272947, 2020). "In summary, these data suggest that the absence of Tgif1 reduces the bone metastatic burden and protects from breast cancer-induced bone destruction in vivo." (PMID 32272947, 2020). "We propose that the lack of Tgif1 in osteoblasts attenuates breast cancer cell migration and metastasis formation, presumably through suppression of Sema3E expression." (PMID 32272947, 2020). "At this time point, we observed single tumor cells and breast cancer micro-metastases in the tibiae of both groups, albeit less frequent in the absence of Tgif1." (PMID 32272947, 2020). "We propose that the lack of Tgif1 in osteoblasts increases Sema3E expression and attenuates breast cancer cell migration as well as metastases formation." (PMID 32272947, 2020). "Hence, our data show for the first time that Tgif1 in osteoblasts supports breast cancer cell migration in a non-cell-autonomous manner." (PMID 32272947, 2020). "Indeed, medium conditioned by control osteoblasts significantly stimulated the migration of breast cancer cells, while medium conditioned by osteoblasts lacking Tgif1 failed to activate breast cancer cell migration." (PMID 32272947, 2020). "Indeed, conditioned medium from osteoblasts of Tgif1−/− mice failed to induce breast cancer cell migration compared to control, suggesting that Tgif1 in osteoblasts augments cancer cell motility." (PMID 32272947, 2020). "Since single breast cancer cells localize not only close to osteoblasts but also nearby Endomucin-positive vascular endothelial cells, we investigated potential alterations of the bone marrow vasculature in non-tumor cell-bearing tibiae from Tgif1+/+ and Tgif1−/− mice." (PMID 32272947, 2020). "Consistently, the absence of Tgif1 impaired the migration of non-small lung cell cancer cells and MDA-MB-231 breast cancer cells in vitro." (PMID 32272947, 2020).
lung carcinoma (5 papers, 2017 to 2026). "TGIF1 can activate Wnt signaling in breast and lung cancer cells, but the mechanism is not very clear." (PMID 29050273, 2017). "In addition, of the genes involved in other cancers, 2/8 are related to gemcitabine: TGIF-1 modifies gemcitabine resistance in bladder cancer, and NKX2-1 higher expression increases gemcitabine cytotoxicity in lung cancer cells." (PMID 29023490, 2017).
colon cancer (4 papers, 2017 to 2026). "The TGIF1 transcription factor gene is present on chromosome 18, which is subject to whole chromosome copy number reduction in colon cancer." (PMID 42039629, 2026). "Here we show that reducing TGIF1 expression in a human colon cancer cell line slows proliferation and reduces growth of orthotopic xenografts." (PMID 42039629, 2026). "Tgif1 has been identified as a stimulator of cancer cell migration as shown by an enhanced migration of colon cancer cells upon overexpression of Tgif1." (PMID 32272947, 2020). "Together, these results strongly indicate that TGIF1 plays a critical role in Wnt signaling by forming a positive feedback loop to sustain high Wnt activity in colon cancer progression." (PMID 29050273, 2017). "Here we identified TGIF1 as a novel tumor promoter in colon cancer, and demonstrated that TGIF1 promotes proliferation and migration of colon cancer cells." (PMID 29050273, 2017). "Importantly, we showed that TGIF1 functions through activating Wnt/β-catenin signaling in colon cancer cells." (PMID 29050273, 2017). "Importantly, TGIF1 could also induce Wnt-induced the Topflash reporter expression in HCT116 colon cancer cells in a dose-dependent manner, in spite that Wnt signaling is constitutively active in these cells due to mutation of β-catenin." (PMID 29050273, 2017).
non-small cell lung carcinoma (4 papers, 2017 to 2022). A group of at least three distinct histological types of lung cancer, including non-small cell squamous cell carcinoma, adenocarcinoma, and large cell carcinoma. "TGIF1 is able to encourage non-small cell lung cancer cells to grow and migrate while TGIF1 knockdown ameliorates tumorigenic characteristics." (PMID 35578338, 2022).
otitis media (4 papers, 2016 to 2020). Inflammation of the anatomical structures of the middle ear, which is most often caused by an infectious process. "Similar placental defects, as well as otitis media were found in a second line of Tgif1 null mice in a pure C57BL/6 strain background." (PMID 27187787, 2016). "Although Tgif1 and Tgif2 single null mice are relatively normal on a mixed strain background, transferring a Tgif1 mutation to a relatively pure C57BL/6 strain results in approximately 50% perinatal lethality of the Tgif1 nulls, placental defects and otitis media in the weaned mice." (PMID 27187787, 2016). "Otitis media are accompanied by raised expression of vascular endothelial growth factor, TNF-α and IL-1β in ear fluids, during which TGIF1 mutants illustrate auditory deficits." (PMID 33414721, 2020). "Both the TGIF1 and FBXO11 loci are thought to be involved in TGF-β signalling, which implies that TGF-β may be critical in the transition from acute to chronic middle ear inflammation, and could be a future target for molecular therapies." (PMID 28970529, 2017).
pancreatic ductal adenocarcinoma (4 papers, 2019 to 2022). An infiltrating adenocarcinoma that arises from the epithelial cells of the pancreas. "Besides, the association between Twist1 and another binding partner TGIF1 is able to inhibit Twist1, whereas this inhibitory effect can be abolished by the phosphorylation of TGIF1 in pancreatic ductal adenocarcinoma." (PMID 35601657, 2022). "The TG-interacting factor 1 (TGIF1) gene, which encodes a nuclear transcriptional corepressor of the TGFβ1/Smad signaling pathway, has been implicated in the pathogenesis of various types of human cancer; however, its role in pancreatic ductal adenocarcinoma (PDAC) has yet to be elucidated." (PMID 31109321, 2019). "The prominent function of TGIF1 has been indicated as the suppression of the TGFβ signaling pathway in the progression of pancreatic ductal adenocarcinoma." (PMID 35578338, 2022).
glioma (3 papers, 2022 to 2025). A benign or malignant brain and spinal cord tumor that arises from glial cells (astrocytes, oligodendrocytes, ependymal cells). "In our present analysis of glioma samples using public databases, we found an association between TGIF1 expression levels and unfavorable clinical features." (PMID 35569122, 2022). "GSEA revealed that the signaling pathways associated with TGIF1 expression in glioma included extracellular matrix receptor‐ and cell cycle‐modulating proteins." (PMID 35569122, 2022). "More importantly, no matter which group TGIF1 is in, it shows that the high expression of TGIF1 is a risk to the prognosis of glioma patients according to the molecular subtypes of gliomas (HR >1)." (PMID 35569122, 2022). "In contrast, our data indicated that TGIF1 promotes the malignant progression of gliomas and is associated with poor prognosis." (PMID 35569122, 2022). "Pearson's correlation analysis was used to analyze the CGGA RNA‐seq data to identify other genes associated with TGIF1 in glioma tissues." (PMID 35569122, 2022). "However, three different datasets consistently showed that the expression of TGIF1 has a significant risk for the prognosis of patients with high‐grade glioma (HR>1)." (PMID 35569122, 2022). "Therefore, it can be concluded that the increased expression of TGIF1 has a significant impact on the overall survival of patients with gliomas and has diagnostic value, especially in high‐grade glioma." (PMID 35569122, 2022). "However, three different datasets consistently showed that high expression of TGIF1 was associated with a reduced overall survival time among patients with high‐grade glioma." (PMID 35569122, 2022). "For example, Scriptaid has also been predicted to be a potential targeting drug that is negatively correlated with the expression of the oncogene TGIF1 in gliomas, which is consistent with our research findings." (PMID 39980564, 2025). "Further exploration of different GEO and Oncomine datasets revealed that TGIF1 was significantly overexpressed in gliomas compared to normal tissue." (PMID 35569122, 2022). "Our findings suggest that TGIF1 is a potentially novel molecular marker of glioma, and provide an additional understanding of the biomolecular characteristics of this disease, including its pathogenesis." (PMID 35569122, 2022). "The expression level of TGIF1 was highest in WHO grade IV gliomas and was lower in WHO grade III tumors and lowest in WHO grade II gliomas." (PMID 35569122, 2022). "Cox analysis confirmed that TGIF1 expression was a significant predictor of poor prognosis in patients with glioma." (PMID 35569122, 2022). "The present study also confirmed that TGIF1 can significantly affect the invasive ability of glioma by wound healing assay and transwell assay." (PMID 35569122, 2022). "Taken together, our study, which is the first to comprehensively analyze TGIF1 in gliomas, revealed it to be a novel oncogene in terms of its association with this disease." (PMID 35569122, 2022). "When considering all grades of gliomas collectively, higher expression levels of TGIF1 correlated with shorter overall survival." (PMID 35569122, 2022). "To investigate the impact of TGIF1 expression on the survival of patients with glioma, we analyzed the correlation between TGIF1 mRNA levels and clinical features associated with glioma prognosis." (PMID 35569122, 2022). "At this point, the critical role of TGIF1 in the malignant progression of glioma has been clearly demonstrated." (PMID 35569122, 2022). "TGIF1 mRNA was markedly elevated in highly malignant gliomas compared to low‐grade counterparts; moreover, the expression of TGIF1 in recurrent gliomas was higher than that in primary gliomas." (PMID 35569122, 2022). "We found that the high expression of TGIF1 in gliomas is closely correlated with clinical characteristics associated with poor prognosis." (PMID 35569122, 2022).
glioma (continued). "Our Cox analysis further revealed that TGIF1 is an independent predictor of the prognosis of patients with glioma." (PMID 35569122, 2022). "In the present study, it is similarly demonstrated that TGIF1 can significantly affect the proliferative capacity of gliomas, suggesting that TGIF1 serves as a clearly therapeutic target to inhibit glioma proliferation." (PMID 35569122, 2022). "TGIF1 was significantly overexpressed in gliomas and was correlated with unfavorable prognostic factors and shorter overall survival." (PMID 35569122, 2022). "RT‐qPCR confirmed that the mRNA expression levels of TGIF1 in glioma cell lines and tissues were markedly increased over controls." (PMID 35569122, 2022). "We aimed to explore the relationship between TGIF1 expression and the clinical characteristics of patients with glioma, including their overall survival." (PMID 35569122, 2022). "Univariate and multivariate analyses suggested that TGIF1 expression is an independent negative prognostic risk factor for patients with all grades of gliomas (hazard ratio [HR] >1)." (PMID 35569122, 2022). "According to the CGGA data, the high expression of TGIF1 significantly shortened the overall survival of patients with IDH mutations regardless of glioma grade and 1p19q codeletion." (PMID 35569122, 2022). "As such, TGIF1 (as a transcriptional regulator) appears to have a multifaceted role in the proliferation, differentiation, metastasis, invasion, and apoptosis of glioma cells, thereby illustrating the complexity of glioma tumorigenesis." (PMID 35569122, 2022). "As such, TGIF1 may be a potential therapeutic target for individualized treatment of patients with glioma." (PMID 35569122, 2022). "We also found that there are many other genes co‐expressed with TGIF1 that may contribute to the malignant progression of glioma." (PMID 35569122, 2022). "We also clarified biological mechanisms of TGIF1 involvement in glioma using GSEA." (PMID 35569122, 2022). "Using the online GEPIA tool, we discovered that the expression levels of TGIF1 in numerous tumor tissues such as glioblastoma multiforme and low‐grade glioma were higher than those in the matched normal tissues; this was also verified using two GEO datasets (GSE4290 and GSE50161)." (PMID 35569122, 2022). "Finally, in vitro experiments demonstrated that knockdown of TGIF1 significantly inhibited the proliferation and invasion of glioma cell." (PMID 35569122, 2022). "Given our evidence that TGIF1 may be involved in the pathological processes of glioma, we further explored the cellular mechanisms potentially involved using GSEA." (PMID 35569122, 2022). "Additionally, recurrent gliomas showed higher expression levels of TGIF1 than primary gliomas; this phenomenon was observed in several histological subtypes." (PMID 35569122, 2022). "Therefore, TGIF1 appears to be a novel prognostic indicator and therapeutic target in patients with gliomas." (PMID 35569122, 2022). "Therefore, it can be confirmed that the high expression of TGIF1 can promote the malignant behavior of glioma cells." (PMID 35569122, 2022). "Hence, we performed this first study of its kind to systematically analyze TGIF1 in glioma and elucidate its biological function as well as its role in patient prognosis using a large sample." (PMID 35569122, 2022). "However, few studies have investigated the role of TGIF1 in gliomas." (PMID 35569122, 2022). "Finally, knockdown of TGIF1 significantly inhibits the proliferation and invasion of glioma cell." (PMID 35569122, 2022). "We first analyzed the expression of TGIF1 in tumors using the GEPIA and Oncomine databases and found that this gene's expression was higher in central nervous system tumors than in normal brain tissues in both databases." (PMID 35569122, 2022).
glioma (continued). "Our analysis of the CGGA RNA‐seq data showed that increased expression of TGIF1 can shorten the survival of patients with glioma regardless of disease grade; this was verified when examining the CGGA microarray and TCGA RNA‐seq data." (PMID 35569122, 2022). "Finally, the high expression of TGIF1 did affect the prognoses of patients of any glioma grade who had wildtype IDH regardless of 1p19q codeletion." (PMID 35569122, 2022). "However, systematic studies of TGIF1 in gliomas have not been performed to date." (PMID 35569122, 2022).
oral squamous cell carcinoma (3 papers, 2017 to 2023). "In oral squamous cell carcinoma, TGIF1 splicing variant 8 was reported to be correlated with the pathologic stage." (PMID 37810965, 2023). "In a study of oral squamous cell carcinomas, transcript TGIF1-008 was over-expressed and TGIF1-005 under-expressed in malignant tissue." (PMID 28335481, 2017).
renal fibrosis (3 papers, 2020 to 2025). A final common manifestation of a wide variety of chronic kidney diseases characterized by glomerulosclerosis and tubulointerstitial fibrosis. "In a previous study, microRNA-101 inhibited renal fibrosis by inhibiting KDM3A expression to regulate TGIF1 expression." (PMID 33414721, 2020). "KDM3A has been detected to downregulate the expression of TGIF1 in renal fibrosis." (PMID 32092824, 2020). "Interestingly, lysine-specific demethylase 3A (KDM3A) enhanced transforming growth factor β-induced factor 1 (TGIF1), inhibited fibronectin, alpha skeletal muscle actin (α-SMA) as well as the phosphorylation of Smad2/3 to curtail renal fibrosis." (PMID 33414721, 2020). "Additionally, the Gene Expression Omnibus (GEO) database revealed that TGFB-induced factor homeobox 1 (TGIF1) of the TGF-β/Smad signaling pathway was found to be differentially expressed in the GEO: GSE66494 dataset, where it was highly expressed in renal fibrosis." (PMID 32092824, 2020). "In addition, miR-101a could target and downregulate KDM3A expression, which led to elevated TGIF1, inhibited expression of Collagen I (Col1a1), fibronectin, α-SMA, YAP1, and TGF-β2 along with the extent of Smad2/3 phosphorylation, as well as delayed renal fibrosis degree." (PMID 32092824, 2020).
acute myeloid leukaemia (2 papers, 2020 to 2024). "TGIF2 has been studied much less in YAPoff cancers, although the paralog TGIF1 suppresses acute myeloid leukemia consistent with our results in neural/neuroendocrine YAPoff cancers." (PMID 39172021, 2024).
bladder cancer (2 papers, 2017 to 2023). "Higher cell migration, reactive oxygen species (ROS) production, TGIF1 and p67phox expression, and AKTs473 phosphorylation were detected in invasive bladder cancer T24 cells as compared to the non-invasive bladder cancer RT4 cells." (PMID 37627900, 2023). "Hence, TGIF1 was found to promote bladder cancer cell migration and invasion, induced the production of ROS, and regulated Nox2 and p67phox expression." (PMID 37627900, 2023).
diabetes (2 papers, 2022 to 2025). "When we analyzed TGFβ-associated genes, we were astonished that several triggers like TGFβ2 and TGFBI were significantly activated by diabetes, while several suppressors like TGIF1 and TGIF2 were significantly deactivated by diabetes." (PMID 35935990, 2022).
endometritis (2 papers, 2016 to 2020). An acute or chronic, usually bacterial infectious process affecting the endometrium. "The expression patterns of only 28 genes in subclinical endometritis have been substantially altered, of which 26 genes including PTHLH, INHBA, DAPL1, MAOB, CXCR4, and TGIF1 were identified in both subclinical and clinical endometritis." (PMID 33426032, 2020).
gastric cancer (2 papers, 2017 to 2023). A primary or metastatic malignant neoplasm involving the stomach. "The functions of TGIF1 in leukemia, gastric cancer and ovarian cancer were also reported." (PMID 29050273, 2017).
hypopituitarism (2 papers, 2020 to 2021). A condition of diminution or cessation of secretion of one or more hormones from the anterior pituitary gland. "In this paper we describe variants in GH1, SOX3 and TGIF1, three genes that are already associated with hypopituitarism." (PMID 34440302, 2021). "Mutations in TCF7L1 and TGIF1 have been reported in patients with hypopituitarism recently." (PMID 33077725, 2020). "TGIF1 (c.268C>T:p.Arg90Cys) was identified in the present study by whole exome sequencing in a patient with features of HPE (MIM # 142946) and combined pituitary hormone deficiency." (PMID 34440302, 2021).